PNPLA3 (patatin like domain 3, 1-acylglycerol-3-phosphate O-acyltransferase )
Diseases named in the same sentence as PNPLA3 in open-access papers (continued):
Sharing a sentence is not in itself a finding about the gene and the disease.
non-alcoholic fatty liver disease (continued). "This occurs through the induction of hepatic lipogenic genes, including patatin-like phospholipase domain-containing protein 3 (Pnpla3), a gene whose polymorphism is associated with the pathogenesis of non-alcoholic fatty liver diseases (NAFLD)." (PMID 33171992, 2020). "Case-control studies assessing the relationship between PNPLA3 rs738409 G/C gene polymorphism with non-alcoholic fatty liver disease in children were selected according to inclusion and exclusion criteria." (PMID 32811452, 2020). "Both PNPLA3 I148M and hepatic inflammation are associated with nonalcoholic fatty liver disease (NAFLD) progression." (PMID 31793207, 2020). "Among the 4 SNPs predicting ALT, rs2954021 (TRIB1) predicts both ALT and ALP, and rs738409 (PNPLA3) is highly associated with non-alcoholic fatty liver disease." (PMID 32045441, 2020). "The PNPLA3 missense variant, rs738409, is the most consistently replicated genetic risk factor for non-alcoholic fatty liver disease." (PMID 31249592, 2019). "A non-synonymous variant (rs738409) of the patatin-like phospholipase domain containing 3 (PNPLA3) gene was first identified to be associated with liver fat content and risk of non-alcoholic fatty liver disease in individuals from various ancestries." (PMID 26389885, 2015). "A GWAS study of the Dallas Heart study population has revealed that a polymorphism of PNPLA3 (rs738409; I148M) is strongly associated with increased hepatic fat levels and susceptibility to nonalcoholic fatty liver disease." (PMID 25617409, 2015). "The main findings demonstrate a small but consistent association of PNPLA3 with non-alcoholic fatty liver disease and non-alcoholic steatohepatitis." (PMID 26462272, 2015). "In contrast, the genes PNPLA3 (adiponutrin), GCKR (glucokinase regulator) and TRIB1 (tribbles homolog 1) were associated with fibrosis phenotypes in non-alcoholic fatty liver disease, with PNPLA3 demonstrating the most consistent effects across studies." (PMID 24586654, 2014). "Further genetic variants in the Patatin like phospholipase-3 (PNPLA3) gene are associated with increased risk of nonalcoholic fatty liver disease." (PMID 24693952, 2014). "Variation in patatin-like phospholipase domain-containing 3 (PNPLA3) gene is associated with disease progression in nonalcoholic fatty liver disease (NAFLD)." (PMID 24349054, 2013). "For example, the I148M variant of the patatin-like phospholipase domain-containing protein 3 (PNPLA3) gene has been associated with increased hepatic fat accumulation, predisposing carriers of this variant to a higher risk of non-alcoholic fatty liver disease (NAFLD) when consuming a high-fat diet." (PMID 40626223, 2025). "African genetic ancestry is associated with a lower frequency of the PNPLA3 allele, a variant which may be a risk factor for non-alcoholic fatty liver disease, suggesting a possible ancestry protective factor." (PMID 39120181, 2024). "Thus, the variant rs738409 in patatin-like phospholipase domain-containing 3 (PNPLA3) has been identified as a risk factor for suffering alcohol-related liver cirrhosis and non-alcoholic fatty liver disease (NAFLD)." (PMID 34068303, 2021). "In addition to the genetic alterations leading to hepatic fibrosis in the childhood, mutations of the PNPLA3 gene represent a major predisposing factor in non-alcoholic fatty liver disease (NAFLD) patients." (PMID 34685739, 2021). "Results from this study suggest that reduction of arachidonic acid and polyunsaturated fatty acid intake might be important for the prevention of non-alcoholic fatty liver disease progression, especially among those with PNPLA3 risk alleles." (PMID 34065978, 2021). "The PNPLA3 protein has lipase activity towards triglycerides in hepatocytes and a loss-of-function polymorphism of this gene has been shown to be strongly associated with nonalcoholic fatty liver disease." (PMID 31374856, 2019).
non-alcoholic fatty liver disease (continued). "Notably, three of the top four weighted loci, GCKR, CILP2/TM6SF2, and PNPLA3 have been previously associated with nonalcoholic fatty liver disease (NAFLD), and functional work has implicated these loci in liver lipid metabolism." (PMID 30240442, 2018). "Furthermore, the well-known alcoholic and nonalcoholic fatty liver disease-associated variant in PNPLA3 rs7384099,19,20 has recently been shown to affect the development of HCC in European individuals with CHC9,10,17." (PMID 28928439, 2017). "Similarly, the reported effect size of the PNPLA3 I148M variant on liver damage in nonalcoholic fatty liver disease was larger in pediatric case series." (PMID 25171251, 2014). "Individuals with PNPLA3 I148M variants, associated with non-alcoholic fatty liver disease, demonstrate differential methylation responses to dietary choline and fermented foods, suggesting that epigenetic regulation may mediate gene–diet effects on liver health." (PMID 41596220, 2026). "A common polymorphism of PNPLA3 (I148M, rs738409), linked to increased PNPLA3 presence on lipid droplets, is a strong genetic determinant of non-alcoholic fatty liver disease (NAFLD) and of its progression." (PMID 33557317, 2021). "Previously, there was a study showing that adiposity significantly increases the effect of the three variants (PNPLA3-I148M, TM6SF2-E167K, and GCKR-P446L) associated with nonalcoholic fatty liver disease (NAFLD)." (PMID 38674389, 2024). "The GG genotype of the Patatin-like phosphatase domain-containing 3 (PNPLA3), dietary fat, short-chain fatty acids (SCFA) and branched-chain amino acids (BCAA) are linked with non-alcoholic fatty liver disease." (PMID 38257154, 2024). "More recently, human fetal hepatocyte organoids were used for modeling free fatty acid loading, interindividual genetic variability (PNPLA3 I148M), monogenic lipid disorders (APOB and MTTP mutations), and induced non-alcoholic fatty liver disease (NAFLD)." (PMID 37146581, 2023). "TCF7L2 rs7903146 and PNPLA3 rs738409 gene variants confer the strongest risk for type 2 diabetes mellitus (T2DM) and non-alcoholic fatty liver disease (NAFLD), respectively." (PMID 35897035, 2022). "Patatin-like phospholipase domain-containing protein 3 (PNPLA3) is a lipase that plays a central role in human non-alcoholic fatty liver disease etiology but has received limited attention in bovine fatty liver research." (PMID 33531537, 2021). "PNPLA3 I148M variant and TM6SF2 E167K variant are recognized as the major genetic modifiers of nonalcoholic fatty liver disease (NAFLD)." (PMID 30738435, 2019). "Recent genome-wide association studies have identified that variants in or near PNPLA3, NCAN, GCKR, LYPLAL1, and TM6SF2 are significantly associated with non-alcoholic fatty liver disease (NAFLD) in multiple ethnic groups." (PMID 27532011, 2016). "Recent reports suggest a role for the Patatin-like phospholipase domain-containing protein 3 (PNPLA3) in the pathology of non-alcoholic fatty liver disease (NAFLD)." (PMID 27128907, 2016). "Non-alcoholic fatty liver disease (NAFLD) represents a heterogeneous and progressive condition with a major pathogenic interplay between both metabolic (e.g., obesity, insulin resistance) and genetic (e.g., PNPLA3 and TM6SF2) factors." (PMID 33806784, 2021). "In addition, mutations in other genes known to predispose for the development of non-alcoholic fatty liver disease, e.g. PPARs, FXR, PNPLA3 weren’t seen in our study." (PMID 34496798, 2021). "In a recent study, the increased risk of HCC and PNPLA3 G allele was found only in alcoholic liver disease, but not in non-alcoholic fatty liver disease or viral hepatitis B and C." (PMID 31527889, 2019). "PNPLA3 non-alcoholic fatty liver disease (NAFLD): a chronic liver disease [recently redefined as metabolic dysfunction-associated steatotic liver disease (MASLD)] that is characterized by excessive fat accumulation within the liver." (PMID 39878508, 2025).
non-alcoholic fatty liver disease (continued). "Multiple lines of evidence suggest that parathin-like phospholipase structural domain 3 (PNPLA3), a member of the parathin-like phospholipase family, is expressed primarily in the liver and adipose tissue and is a key factor in the pathogenesis of nonalcoholic fatty liver disease (NAFLD)." (PMID 35624499, 2022). "For example, the common PNPLA3 p.I148M, MBOAT7 p.G17E, and TM6SF2 p.E167K variants have been shown to increase the risk of liver steatosis, fibrosis, and cirrhosis in patients with nonalcoholic fatty liver disease (NAFLD), alcoholic liver disease (ALD), and with viral liver diseases." (PMID 34949757, 2021). "Non-alcoholic fatty liver disease (NAFLD) is thought to emerge from a state of insulin resistance (IR) as the product of an interaction between the obesogenic environment and genetically predisposing alleles (e.g., I148M in PNPLA3, E167K in TM6SF2, MBOAT7 rs641738 variant)." (PMID 31426291, 2019). "In contrast to studies documenting association of the PNPLA3 rs738409 genotype with the risk of HCC development in alcoholic liver disease and non-alcoholic fatty liver disease, no such association was found in HCV-infected subjects." (PMID 31527889, 2019).
Insulin resistance (103 papers, 2009 to 2026). Increased resistance towards insulin, that is, diminished effectiveness of insulin in reducing blood glucose levels. "Key pathogenic mechanisms involve insulin resistance, adipokine imbalance, gut-liver axis dysregulation, and genetic polymorphisms such as PNPLA3." (PMID 40734888, 2025). "In PNPLA3 genetic variant carriers, early recognition, aggressive intervention, and improved insulin resistance should be required." (PMID 40507973, 2025). "Previous studies have shown that adiposity and insulin resistance synergise with the PNPLA3 p.I148M variant in determining the development and progression of MASLD." (PMID 38224202, 2024). "Insulin resistance (IR), type 2 diabetes (T2D), and the polymorphisms patatin-like phospholipase domain-containing 3 (PNPLA3) rs738409 and transmembrane 6 superfamily member 2 (TM6SF2) rs58542926 are independent risk factors of NASH." (PMID 35625751, 2022). "The major strengths of our study were the large sample size with comprehensive assessments of multiple NAFLD risk factors, such as visceral adiposity, insulin resistance, and PNPLA3, and the inclusion of an HIV-uninfected comparator group." (PMID 32128321, 2019). "The novelty of our analysis resides not only in the PNPLA3 148M allele being associated with type 2 diabetes but also simultaneously with lower serum triglycerides and increased insulin resistance." (PMID 22724004, 2012). "In HCV genotype 2 infected patients carrying the PNPLA3 148M allele, there was significantly increased insulin resistance (P = 0.023) and lower viral load (P = 0.005) at baseline as well as the first seven days of antiviral treatment." (PMID 22978414, 2012). "This is the first study showing that the PNPLA3 148M allele is associated with insulin resistance and increased type 2 diabetes risk specifically in severely obese individuals despite relatively lower serum triglycerides." (PMID 22724004, 2012). "The PNPLA3 148M variant was associated with a higher risk of being insulin resistant (Odds ratio, O.R.: 1.10, 95% Confidence interval, C.I. 1.02-1.35, P = 0.038)." (PMID 22724004, 2012). "PNPLA3 148M allele carriers were found to have increased insulin resistance in HCV genotype 2 infected patients (Padd = 0.023, Prec = 0.005)." (PMID 22978414, 2012). "The main finding of the present study is the association between the PNPLA3 148M allele and increased insulin resistance and lower baseline viral load among HCV genotype 2 infected patients." (PMID 22978414, 2012). "In this study an association between increased insulin resistance and the PNPLA3 148M allele was observed." (PMID 22978414, 2012). "The novel association at PNPLA3 reinforces the importance of insulin resistance-related processes in the regulation of sICAM-1 levels." (PMID 21533024, 2011). "Studies indicate ethnic disparities in NAFLD pathogenesis – for instance, African Americans exhibit distinct hepatic insulin resistance patterns compared to East Asians at comparable BMI levels, likely influenced by genetic variants such as PNPLA3 and TM6SF2 with population-specific effects." (PMID 40228278, 2025). "Additionally, those with the PNPLA3 148M allele have lower triglyceride levels, increased insulin resistance, and greater vulnerability to diabetes." (PMID 40917348, 2025). "PNPLA3 rs738409 G allele carriers reportedly exhibit worse insulin resistance." (PMID 40074353, 2025). "A limitation of our study is that whether PNPLA3-driven liver fat accumulation causes liver insulin resistance cannot be determined here." (PMID 39801107, 2025). "PNPLA3 rs738409 risk genotype completely decoupled the direct correlation between two surrogate markers of insulin resistance: TyG and HOMA2-IR confirming our hypothesis." (PMID 36944955, 2023). "The effect of high BMI in enhancing NASH risk in PNPLA3 I148M carriers may be mediated by insulin resistance." (PMID 36035124, 2022).
Insulin resistance (continued). "Furthermore, we examined if PNPLA3 I148M variant affects changes in insulin resistance, triglyceride and transaminase levels." (PMID 22724004, 2012). "In the present study, we could not detect a significant association between PNPLA3, FFAs, and insulin resistance, whereas in line with the experimental hypothesis PNPLA3 genotype influenced serum adiponectin levels." (PMID 22898488, 2012). "One study of a variant in the patatin-like phospholipase-3 (PNPLA3)/adiponutrin gene (rs738409 C.G) found that carrying the G allele (n = 96) compared with being a CC homozygote (n = 104) was associated with lower fasting insulin, insulin resistance, and LGA132." (PMID 38110524, 2023). "Previous studies showed that the PNPLA3 rs738409 C > G variant reduced the hydrolysis of fatty acids and enhanced the transacylase activity of this enzyme for phospholipids, leading to the accumulation of fatty acids, TGs, and cholesterol in hepatocytes, and increased insulin resistance." (PMID 37400794, 2023). "Interestingly, for these patients with TT of the rs3810622 locus exhibited higher ALT and GLU, perhaps suggesting that polymorphisms of PNPLA3 gene may be associated with insulin resistance in addition to liver damage." (PMID 27537584, 2016). "Thus, it is likely that genetic vulnerability is of importance and it is possible that PNPLA3 variation may play a role It has been shown that both genetic variants and insulin resistance regulate adipose PNPLA3 gene expression." (PMID 19390624, 2009). "Notably, while the PNPLA3 rs738409 variant is consistently implicated in hepatic lipid accumulation and fibrosis, its association with systemic metabolic syndrome features such as insulin resistance and T2DM remains inconsistent, a pattern mirrored in our findings." (PMID 40981175, 2025). "The PNPLA3 genotype showed an association with the HOMA-IR * and insulin resistance in adipose tissue." (PMID 37632067, 2023). "NAFLD associated with PNPLA3 I148M had higher levels of hepatic polyunsaturated triacylglycerols, compared to NAFLD associated with insulin resistance which had higher levels of saturated and mono-unsaturated triacylglycerols, free fatty acids and ceramides." (PMID 36035124, 2022). "In some studies, the relationship between PNPLA3 SNP rs738409 and insulin resistance was also discussed." (PMID 34476007, 2021). "In obesity and insulin resistance conditions, PNPLA3 expression is induced by insulin and hepatocytes and hepatic stellate cells, and localizes at the surface of lipid droplets." (PMID 31375010, 2019). "Contrastively, PNPLA3 rs1010023 protects them from glucose dysregulation by attenuating the insulin resistance, probably on the basis of BMI reduction." (PMID 28695131, 2017). "After feeding, Steroid Regulatory Element Binding Protein-1c, the master regulator of lipogenesis, induces production of PNPLA3 in the liver; PNPLA3 is also induced during insulin resistance." (PMID 25290313, 2014). "The hepatic PNPLA3 expression level was also correlated with insulin resistance as assessed by homeostatic model assessment of insulin resistance index (HOMA-IR)." (PMID 23175050, 2013). "The PNPLA3 rs738409 genotype GG might promote liver fat and fibrosis by worsening insulin resistance, in addition to direct hepatic fattening and fibrosis effects, compared to other genotypes." (PMID 40074353, 2025). "In particular, the effects on impaired lipid transport from the liver, specifically reduced VLDL-1 levels, are already apparent in the fasting state, suggesting that pronounced insulin resistance may consistently enhance the effect of PNPLA3 148M." (PMID 40677694, 2025). "These genetic polymorphisms are genes implicated in the regulation of lipid accumulation in hepatocytes, oxidative stress, insulin resistance and fibrogenesis A high-frequency gene variant in MASLD is the PNPLA3 (Patatin-like phospholipase domain-containing protein 3) allele rs738409[G]." (PMID 41311807, 2025).